BACH1 (BACH transcriptional regulator 1)
Diseases named in the same sentence as BACH1 in open-access papers (continued):
Sharing a sentence is not in itself a finding about the gene and the disease.
cancer (continued). "Here, we first investigated whether RKIP and BACH1 show antagonistic trends across different cancer types using transcriptomic data from The Cancer Genome Atlas (TCGA)." (PMID 37963558, 2023). "Similarly, the ssGSEA scores of PD-L1 gene signature correlated negatively with RKIP in 68.57% (24 out of 35) but positively with BACH1 in 88.57% (31 out of 35) of the cancer types." (PMID 37963558, 2023). "In addition, we use the CPTAC database to analyze differences between BACH1 expression level in primary cancer tissues and normal tissues." (PMID 35651942, 2022). "According to a previous study, BACH1 has shown complex function in cancer." (PMID 34351577, 2022). "However, as a retrospective study, the predictive value of BACH1 in cancer prognosis needs to be validated by both basic and clinical studies." (PMID 35651942, 2022). "In this study, we uncovered the capacity of BACH1 as a new pan-cancer therapeutic target." (PMID 35651942, 2022). "Taken together with these reports, our findings suggested that TBK1 may promote EMT and metastasis of cancer cells via both BACH1-independent and BACH1-dependent mechanisms." (PMID 36009179, 2022). "BACH1 expression is regulated at translational or post-transcriptional levels in cancer cells." (PMID 35154476, 2022). "Overall, our data shed light on BACH1’s effect on latent utility in cancer targeting therapy." (PMID 35651942, 2022). "Exploring the regulation of the E-cadherin gene by BACH1 may be beneficial to elucidating the pathological roles of BACH1 in cancer proliferation and metastasis, as well as in the search for new therapeutic approaches." (PMID 36009179, 2022). "The higher BACH1 expressed, the worse overall survival of cancer patients would have." (PMID 35651942, 2022). "BACH1’s expression significantly varies in different cancer types." (PMID 35651942, 2022). "Especially, it will be important to investigate whether the repression of epithelial genes by BACH1 in cancer cells also involve epigenetic rewriting of the target genes." (PMID 34339740, 2021). "The recent research summarized here has established the critical roles of BACH1 in cancer." (PMID 34339740, 2021). "As briefly mentioned earlier, BACH1 plays a role for macrophage metabolism, which might be critical for communication between cancer and tumor-infiltrated macrophages." (PMID 33809182, 2021). "Although BACH1 has been reported as a crucial regulator of metastasis in various cancers, its role in ESCC remains unknown." (PMID 33932125, 2021). "To frame these issues in previous findings, we propose a “two-faced BACH1 model” in cancer." (PMID 34339740, 2021). "Furthermore, inhibition of BACH1 decreased antioxidant-induced glycolysis rates as well as reduced migration and invasion of cancer cells, suggesting BACH1 as a potentially useful cancer therapeutic target." (PMID 33809182, 2021). "We propose a “two-faced BACH1 model” to integrate diverse functions of BACH1 in cancer cells." (PMID 34339740, 2021). "Pharmacological or genetic inhibition of BACH1 could reprogram by increasing mitochondrial metabolism, subsequently rendering metabolic vulnerability of cancer cells against mitochondrial respiratory inhibition." (PMID 33809182, 2021). "In particular, blockade of BACH1 using either approach including shRNA, sgRNA, or small inhibitors such as hemin, reduced BACH1 levels in cancer cells and reduction of BACH1 was sufficient to successfully and efficiently inhibit metastasis processes of cancer cells." (PMID 33809182, 2021). "Therefore, BACH1 is two-faced in that it promotes cancer progression at the expense of stress resilience." (PMID 34339740, 2021). "The multifaceted roles of BACH1 in cancer biology should be further explored." (PMID 34339740, 2021).
cancer (continued). "The roles of BACH1 in reprogramming of cancer cell metabolism have been reviewed recently." (PMID 34339740, 2021). "Additional mechanisms are also involved in the promotion of cancer progression by BACH1." (PMID 34339740, 2021). "One of the most important points is that BACH1 may function as a regulator modulating the cell fate of cancer cells and an inducer of cancer cell plasticity." (PMID 34339740, 2021). "In addition to transcriptional regulation, BACH1 is also involved in epigenetic regulation of cancer cells." (PMID 33809182, 2021). "Recent several studies identified a new functional role of BACH1 in cancer metabolism regulation." (PMID 33809182, 2021). "The promotion of ferroptosis by BACH1 via multiple pathways may provide a therapeutic strategy for cancers." (PMID 34339740, 2021). "We then summarize recent findings on the function of BACH1 in cancer cells and examine how the properties of cancer cells, including EMT, altered metabolism, metastasis, angiogenesis, and epigenetics, can be explained based on the established and/or putative BACH1 target genes." (PMID 34339740, 2021). "Cancer cells with a high expression of BACH1 may be more sensitive to ferroptosis-inducing drugs than those with low BACH1 levels." (PMID 34339740, 2021). "It will be important to investigate unique and overlapping target genes of BACH1 in cancer cells." (PMID 34339740, 2021). "Recently, BTB and CNC homology 1 (BACH1), a heme-regulated transcription factor that represses genes involved in iron and heme metabolism in normal cells, was shown to shape the metabolism and metastatic potential of cancer cells." (PMID 34339740, 2021). "Considering that cellular senescence is a tumor suppressor mechanism, BACH1 may promote carcinogenesis and cancer growth by suppressing cellular senescence." (PMID 34339740, 2021). "Subsequently, mitochondrial respiratory inhibitors such as metformin, rotenone, and antimycin A could be even more lethal to the survival of cancer cells that are depleted with BACH1 compared to the BACH1-enriched control." (PMID 33809182, 2021). "Does the function of BACH1 in mitosis contribute to cancer progression?" (PMID 34339740, 2021). "However, knockout of Bach1 using single-guide RNA (sgBach1) normalized ATP levels, invasiveness, and metastasis of antioxidant-treated cancer cells to the levels of control cells." (PMID 33809182, 2021). "While recent studies identified new roles of BACH1 in the primary cancer metabolism, there are still other metabolic pathways regulated by BACH1 to understand, including: one carbon metabolism, amino acid metabolism, pentose phosphate pathway, and fatty acid oxidation." (PMID 33809182, 2021). "BACH1 in not only cancer cells but also surrounding stromal cells regulates angiogenesis." (PMID 34339740, 2021). "Therefore, BACH1 promotes the invasiveness of cancer cells by enhancing their ability to degrade extracellular matrix and increasing their motility." (PMID 34339740, 2021). "Interestingly, a new function of BACH1 has been identified in metabolic reprogramming in breast and lung cancer." (PMID 33499022, 2021). "We additionally consider how other features of cancer cells, such as their dynamics and plasticity, and ferroptosis (iron-dependent cell death) may be shaped by BACH1." (PMID 34339740, 2021). "Accumulating data establish BACH1 as a critical facilitator of tumorigenesis and metastasis in breast, colon, prostate ovarian, and lung cancer." (PMID 32132179, 2020). "In conclusion, MIR17HG was downregulated in NSCLC and may upregulate miR-142-3p through methylation pathway to promote its expression, thereby downregulating Bach-1 and suppress cancer cell invasion and migration." (PMID 32228546, 2020). "In addition, overexpression of BACH1 in human ovarian ES2 carcinoma cells induces a significant increase in VEGFC expression, strongly supporting a genetic and functional link between these two factors." (PMID 32132179, 2020).
cancer (continued). "Heme accelerates BACH1 decay, and we can use the self-repressing model to develop a strategy that reduces both the expected amounts of BACH1 within the cells and their fluctuations to increase cancer treatment effectiveness." (PMID 30281699, 2018). "Bach1 is also involved in epigenetic mechanisms of cancer progression." (PMID 30370001, 2018). "Six BACH1 germ line alterations were observed in the mutation analysis, but none of these were found to associate with the cancer phenotype." (PMID 16430786, 2006). "Therefore, targeting BACH1 has emerged as a promising strategy for cancer treatment." (PMID 40278267, 2025). "This method could address and advance the limitation of our current analysis, as correlation analyses using tumor tissues containing heterogeneous cancer cell populations cannot access the possibility of exclusive expression between BACH1 and MCT1 at the single-cell level." (PMID 40710214, 2025). "However, few articles systematically summarized the roles of BACH1 in cancer." (PMID 38321558, 2024). "Thus, BACH1 plays a critical role in the EMT process of various cancers." (PMID 38321558, 2024). "By unveiling the multifaceted regulatory mechanisms of BACH1 stability, our studies highlight the abilities of ubiquitin ligases to decode high-order protein assemblies and reveal therapeutic opportunities to block cancer invasion via compound-induced BACH1 destabilization." (PMID 38895309, 2024). "Thus, BACH1 leads to a concentration gradient between cell membranes with low oleic acid content and lymph fluid with high oleic acid, resulting in the chemoattraction of cancer cells and metastasis via lymph vessels." (PMID 38321558, 2024). "Thus, BACH1 regulates lactate efflux or influx, presenting promising targets for cancer treatment." (PMID 38321558, 2024). "It indicates that combined inhibition of ETC and BACH1 may effectively treat cancer." (PMID 36902385, 2023). "Overall, our pan-cancer systems-level analysis reveals that RKIP and BACH1 can control multiple axes of plasticity (EMT, metabolic reprogramming, stemness) together in opposite directions, thus explaining their association with patient survival seen across cancer types." (PMID 37963558, 2023). "However, different BACH1 downstream targets have been reported in certain kinds of cancer types." (PMID 36453019, 2023). "Besides, BACH1 also participates in epigenetic modification to promote the progression of cancer." (PMID 35651942, 2022). "In addition, BACH1 possesses the ability to restrict cancer progression under some conditions." (PMID 34339740, 2021). "Therefore, BACH1 may also promote the expression of stem cell–like properties in cancer cells by stabilizing pluripotency transcription factors." (PMID 34339740, 2021). "Thus, the presumed differences in the activity of BACH1 may confer unique vulnerabilities to cancer cells." (PMID 34339740, 2021). "Therefore, targeting BACH1 in cancer to suppress its levels might be beneficial to the cancer patients since BACH1 suppression could decrease tumor metastasis and increase metastasis-free survival of cancer patients." (PMID 33809182, 2021). "Cancer cells may utilize such an interaction to convert BACH1 into an activator." (PMID 34339740, 2021). "BACH1 may also inhibit tumor initiation and cancer cell proliferation at an earlier stage." (PMID 34339740, 2021). "BACH1 may further affect the destination of metastasizing cancer cells." (PMID 34339740, 2021). "Altogether, BACH1 may play a conserved role for mitochondrial metabolism in diverse cancer types." (PMID 33809182, 2021).
cancer (continued). "Therefore, cancer cells, which express BACH1 at elevated levels, may be more sensitive to alterations in protein homeostasis and proteasome inhibitors because of the reduced expression of proteasome subunit genes." (PMID 34339740, 2021). "Redox regulation is governed by key antioxidant pathways, such as the BACH1 and NRF2 pathways, along with transcriptional factors that significantly affect cancer progression and immunotherapy response." (PMID 40563308, 2025). "Recent studies have demonstrated that BACH1 promotes metastasis and EMT in multiple types of cancers." (PMID 41284701, 2025). "This suggests that the inhibition of BACH1 can modulate the metabolic profile in resistant cancers such that the OXPHOS pathway is restored, glycolysis is reduced or omitted, cancer growth is halted, and cancer cells are sensitized to therapy." (PMID 38255314, 2024). "In contrast, BACH1 exerts its pro-ferroptotic role by modulating the expression of genes (e.g., FTH1) involved in key regulatory pathways of ferroptosis in cancer cells." (PMID 39090114, 2024). "We observed that among 35 cancer types, PD-L1 expression correlated negatively with RKIP expression in 22 of them and positively with BACH1 in 32 of them." (PMID 37963558, 2023). "This study suggests that BACH1 is a potential biomarker and therapeutic target for resistance to proteasome inhibitor chemotherapy in CCA and other cancers." (PMID 37228820, 2023). "To explore the difference of BACH1 at the level of pan-cancer, we use TIMER2.0 to compare the expression levels of BACH1 in cancer tissues and the corresponding normal tissues of 33 cancer." (PMID 35651942, 2022). "We also found that BACH1 is relevant to PD1/L1, the TCR signaling pathway, Th17, and differentiation in some cancer types." (PMID 35651942, 2022). "In this context, RKIP and BACH1 cooperate, in cancer cells, to the onset of two stable states namely, an anti-metastatic state with high RKIP-low BACH1 and a pro-metastatic state with low RKIP-high BACH1 expression." (PMID 36291854, 2022). "Some genes played poor-prognostic factors in cancers, for example, ATF4 in ACC, BACH1 in LGG and UVM, and FOSL1 in DLBC and UVM." (PMID 35242279, 2022). "Tumor tissues exhibited significant colocalization of MAFF and HIF-1 (66% colocalization), MAFF and IL11 (94% colocalization), and BACH1 and IL11 (75% colocalization), suggesting their interactive role in cancer." (PMID 34262028, 2021). "Heme also binds to and destabilizes Bach1, a transcription regulator that controls expression of several groups of genes important for glycolysis, ETC, and metastasis of cancer cells." (PMID 34807950, 2021). "Different from its epigenetic repression in lung and many other cancer cells, PDLIM2 expression in AMs and monocytes is downregulated by ROS-activated BACH1." (PMID 33539325, 2021). "Taken together, these data indicate that BACH1 is a new common mechanism involved in OXPHOS repression and metabolic switch in cancer." (PMID 33499022, 2021). "BACH1 regulates primary metabolic processes such as aerobic glycolysis, mitochondrial OXPHOS, the TCA cycle and redox regulation of cancer cells." (PMID 33809182, 2021). "The mutually suppressive regulatory network between BACH1 and RKIP represents bi-stability, indicating that a tight balance between BACH1 and RKIP expression is needed to coordinate metastasis process of cancer cells." (PMID 33809182, 2021). "Because EMT requires both sufficient BACH1 and SNAI2 for the repression of epithelial genes, such a GRN precludes spontaneous EMT in cancer cells: EMT ensues only when enough BACH1 and SANI2 have accumulated within cells." (PMID 34339740, 2021). "BACH1, as a member of cap ‘n’ collar (CNC) and basic region leucine zipper factor family, has been reported to participate in cancer progression." (PMID 32774161, 2020). "Hence, BACH1 and VEGFC may serve as candidate diagnostic biomarkers in cancer patients." (PMID 32132179, 2020).
cancer (continued). "Through VENN analysis, we detected 603 upregulated and 1043 downregulated DEGs overlapping in the three cancer cell lines, including 16 upregulated TFs (e.g., HOXA2, HOXB2, HOXC10, and NKX2-1) and 36 downregulated TFs (e.g., BACH1 and CDX1), respectively." (PMID 32156290, 2020). "Recent research has revealed that BACH1 plays a crucial role in shaping the metabolic and metastatic potential of cancer cells during cancer progression, irrespective of its antagonism with NRF2." (PMID 41284701, 2025). "Furthermore, recent studies have identified BACH1 as a target of CDDO-Me, whose inhibition suppresses cancer cell invasion." (PMID 41462606, 2025). "We also identified SOD1 and BACH1, involved in regulating cellular responses to oxidative stress, and transcription factor RUNX1 that can regulate cancer cell proliferation and metastasis." (PMID 40018643, 2025). "BACH1 is involved in promoting metastasis by upregulating pro-metastatic genes such as HK2, GAPDH, CXCR4, MMP1, MMP13, and VEGF, and promotes the metastasis of cancer cells in vitro and in vivo." (PMID 40263598, 2025). "As previously shown, the lack of BACH1 target genes conservation across different cancer types and even between cell lines derived from the same cancer type is a significant limitation." (PMID 40716152, 2025). "In addition, BACH1 participates in the regulation of metabolism via suppressing OXPHOS while stimulating glycolysis, thus leading to the Warburg effect in the cancer cells." (PMID 41284701, 2025). "BACH1 is positively related to a high level of monocyte-myeloid-derived suppressor cells (Mo-MDSCs) in TNBC, which means that BACH1 may help cancer cells escape from immunosurveillance and repress immune overreaction, thus promoting tumorigenesis." (PMID 38321558, 2024). "Our studies suggest that compounds that could modify the BTB or DNA-binding domains of BACH1 have the potential to promote the ubiquitination and degradation of BACH1 by FBXL17 or FBXO22, thereby, ameliorating BACH1-mediated cancer metastasis." (PMID 38895309, 2024). "The BACH1 expression and TMB was significantly correlated in 4 cancer types." (PMID 35651942, 2022). "To further analyze BACH1 expression in some cancer types lacking corresponding normal tissue data in the TCGA database, we combined the normal tissue data from GTEx and TCGA databases." (PMID 35651942, 2022). "At the transcriptional levels, BACH1 directly regulates the expression of the mitochondrial electron transport chain (ETC) genes pyruvate dehydrogenase kinases, hexokinase 2 and glyceraldehyde 3-phosphate dehydrogenase in cancer cells." (PMID 35406740, 2022). "Although MPCs are not directly regulated by BACH1, the blockade of MPCs using a small inhibitor with hemin more effectively reduced cancer cell viability." (PMID 35406740, 2022). "The effect of this transcription-independent function of BACH1 on cancer biology has not yet been reported." (PMID 34339740, 2021). "Considering the requirement for BACH1 in metastasis of various cancers, BACH1 may be one of factors that establishes the early stages of EMT in cancer cells." (PMID 34339740, 2021). "This correlation may indicate the potential ability of BACH1 and VEGFC to promote cellular migration and cancer invasion." (PMID 32132179, 2020). "Because Bach1 protein nuclear exportation and subsequent degradation is controlled by tyrosine phosphorylation, we assumed that tyrosine kinase inhibitors would reverse DHA-induced Bach1 degradation and block HO-1 induction by DHA, thus leading to enhanced cytotoxicity upon cancer cells." (PMID 30367621, 2018). "Our experimental results demonstrate that pretreatment of cancer cells with Sorafenib reverses DHA-induced suppression of nuclear Bach1 expression and attenuate DHA-induced HO-1 gene transcription, resulting in a synergistic action that suppresses cancer cell viability and tumor growth." (PMID 30367621, 2018).